POLE (DNA polymerase epsilon, catalytic subunit)
Diseases named in the same sentence as POLE in open-access papers (continued):
Sharing a sentence is not in itself a finding about the gene and the disease.
tumor (continued). "A similar propensity was observed in the POLE-category group and these were especially accumulated in tumours harbouring POLE p.P286R and p.V411L." (PMID 29880869, 2018). "We expected that the four genes (SACS, LRP2, WDR87, and XIRP2) that were detected in all POLE category tumours with POLE p.P286R or p.V411L would exhibit high PS if this score reflected an accumulation of biased mutation patterns." (PMID 29880869, 2018). "For this analysis, we combined our cohort of POLE‐mutant tumours with POLE‐mutant cases from TCGA, using MMR‐P and MMR‐D TCGA cases as comparators." (PMID 29604063, 2018). "Importantly, tumors containing mutations in HR genes, MMR genes, or POLE contained significantly higher mutational load than DNA repair wildtype tumors, and similarly contained significantly increased infiltration by many of the T cell types and other immune cells desirable for anti-tumor activity." (PMID 29487705, 2018). "We found strong similarity of the HT115 whole-genome SNV spectrum with tumor samples sharing POLE deficiency and, among COSMIC exome mutation signatures, to the COSMIC POLE signature." (PMID 30459213, 2018). "Tumors with MSI-H or mutations in POLE or POLD1 genes, which carry an extraordinarily excessive number of somatic genetic events, compose only a small proportion of human neoplasms." (PMID 30211169, 2018). "In POLE-category tumours derived from ICGC data, POLE and PTEN accumulated POLE-independent mutations." (PMID 29880869, 2018). "The analyses performed by the TransPORTEC consortium on 116 high-risk ECs, published also in 2017, confirmed that POLE-mutant and MSI-H tumors are characterized by higher numbers of tumor-infiltrating T cells." (PMID 29163851, 2017). "Three cases (2.2%) were associated with a hypermutated profile that was corroborated with findings of high tumor mutational burden (TMB): 2 cases with MSI-H and 1 case with a POLE mutation." (PMID 28178681, 2017). "In this study we demonstrate the presence of high numbers of tumor-infiltrating T cells in POLE-mutant and MSI tumors, both predicted to be neoantigen-rich, from a clinically relevant cohort of high-risk EC patients." (PMID 28344870, 2017). "By doing so, a slight increase of the total number of substitutions in the tumor DNA from the p.Val474Ile germline carrier was detected when compared with the POLE wild-type MMR proficient tumors." (PMID 28423643, 2017). "To evaluate the role of POLE mutations in colorectal carcinogenesis, namely in advanced CRC, we searched for somatic mutations by Sanger sequencing in tumor DNA samples from 307 cases." (PMID 29072370, 2017). "POLE-ultra-mutated and MSI-H ECs showed an active TME expressing high number of neo-antigens and an elevated amount of tumor infiltrating lymphocytes (TILs)." (PMID 29163851, 2017). "These initial findings have recently been extended to other unselected EC cohorts, in which high densities of peritumoral and tumor-infiltrating T-lymphocytes have been described in POLE-mutant tumors." (PMID 28344870, 2017). "In this sense, when comparing with POLE-exonuclease mutant CRC tumor samples present in the COSMIC database (e.g. TCGA-CA-6718-01, P286R, 5,946 substitutions; and TCGA-A6-6141-01, p.S297F, 1,981 substitutions), a hypermutated profile was not evident." (PMID 28423643, 2017).
tumor (continued). "Variants in POLE and POLD1 are known to increase the somatic mutation rate in tumours, thereby increasing the risk of tumour development." (PMID 28331556, 2017). "POLE mutations were detected in 48 of 788 (6.1%) ECs from PORTEC-1 and-2 and were associated with high tumor grade (P < .001)." (PMID 25505230, 2015). "Exome sequencing data from CRCs and ECs with somatic POLE EDMs show that the coding regions alone of these tumours have acquired a mean of about 5000 somatic base substitutions 1,5." (PMID 23447401, 2013). "While HLA‐I loss showed no significant prognostic impact in POLE, MMRd or p53abn tumours, it significantly correlated with worse disease‐free survival in NSMP tumours (P < 0.001)." (PMID 40792549, 2026). "Additionally, we found 50% of the tumour-matched SAPCS POLE, POLQ, and POLG carriers to present with an above median TMB." (PMID 41038821, 2025). "Whether tumor recurrence is related to mutations in MKNK1, POLE, RET, RTEL1, RUNX1T1, TAP1 still requires further research for validation." (PMID 40901169, 2025). "For example, POLE-mutant tumors are characterized by an exceptionally high tumor mutational burden (TMB) and strong neoantigenicity, which result in robust T-cell infiltration and immunogenic tumor microenvironments." (PMID 41583426, 2025). "However, germline POLE alterations in this tumor are rare, since they have been reported only in 0.25-4% of EC cases." (PMID 40936703, 2025). "The tumor spectrum in PPAP also varies depending on the causal gene, POLD1 or POLE." (PMID 41487566, 2025). "Two cases are caused respectively by somatic mutations in the mismatch repair (MMR) system or POLE gene in tumor cells without clear family history of hereditary disease." (PMID 41278281, 2025). "In addition, POLE and POLD1 mutations are associated with defective DNA repair, resulting in hypermutated phenotypes characterized by high TMB and increased tumor-infiltrating lymphocytes (TILs)." (PMID 41019039, 2025). "Other promising markers include POLE/POLD1 mutation and tumor-infiltrating lymphocytes (TILs)." (PMID 41294832, 2025). "Patient ACCC_CRC_15, the only MSI sample in this cluster, also showed an overall trend of under‐activation in the majority of estimated pathway and TF activities, whereas the EGFR signaling cascade and MYC TF were found significantly over‐activated in this POLE‐mutant tumor." (PMID 39876058, 2025). "Also a rare patient subgroup with mutations in polymerase ε (POLE) or δ1 (POLD1), associated with a hypermutated phenotype and mostly observed in microsatellite-stable (MSS)/MMR-proficient tumours, shows ICB responsiveness." (PMID 38664577, 2024). "Furthermore, POLE mutations have predictive value in CRC patients and are associated with increased levels of immune cell infiltration, potentially enhancing tumor sensitivity to immune therapy." (PMID 39839672, 2024).
tumor (continued). "Indeed, studies by us and others have proposed that there are microsatellite stable (MSS) tumours with a similar tumour immune profile as MSI tumours, e.g., the POLE mutated CRCs." (PMID 38040818, 2024). "POLE and POLD1 genes encode the catalytic subunits of DNA polymerase ε and δ, respectively, which play an important role in DNA replication and correction, and their mutations directly affect the occurrence and development of tumours." (PMID 39530091, 2024). "Given how the presence of a POLE-EDM mutation impacts the outcome and especially the therapeutic approach in EC, this raises the question—does this impact and approach generalize to other tumor entities?" (PMID 39239272, 2024). "CRC patients with POLE mutation were reported to have positive treatment responses with immune checkpoint inhibitors, partly because of the high CD4+ T cell infiltrations and increased expressions of pro-inflammatory cytokines in the tumor microenvironment." (PMID 39007151, 2024). "None of the OCS examined harbored pathogenic POLE exonuclease domain mutations, although one tumor was found to have a non-sense mutation (Q1625X) outside of exonuclease domain." (PMID 39220645, 2024). "Immunogenomic studies have, however, shown that not only hypermutated tumours (MSI or POLE mutated) but also some non-hypermutated MSS tumours display high neoantigen load and tumour immune cell infiltration." (PMID 38040818, 2024). "This prospective clinical trial evaluated the anti-tumor effect of toripalimab in non-MSI-H patients with unselective POLE/POLD1 mutations." (PMID 39218995, 2024). "Among the pMMR/MSS CRC patients without POLE mutations, a median of three somatic mutations (range: 0–8) per tumor were detected." (PMID 38888366, 2024). "The other pathogenic mutation found in our analysis was in the POLE gene of another patient with a non-paired acquired resistant tumor lesion." (PMID 38280045, 2024). "We describe in detail that the sole presence of a POLE variant is not sufficient to classify a tumor as POLEmutated or to classify a POLE mutation as pathogenic." (PMID 39239272, 2024). "It was recently reported that besides tumor DNA, increased mutation loads were also found in normal tissue from individuals with germline POLE mutations although they do not display obvious signs of premature aging." (PMID 37891003, 2024). "The found increased immunogenicity of some MSS tumours has been corroborated by other studies, including but not restricted to POLE-mutated tumours." (PMID 39613865, 2024). "Mutations in POLE and a frameshift deletion in BRCA1 were observed in the parental tumor tissue in each of the six cases, and additional genomic alterations, which were not apparently related to histopathological and immunohistochemical alterations, were found in the PDXs of these cases." (PMID 37231035, 2023). "Moreover, recent data suggested the occurrence of an abundance of tumor-infiltrating lymphocytes (TILs) in POLE/POLD1-mutant CRCs." (PMID 36980791, 2023).
tumor (continued). "In addition to mismatch repair deficiency (MMR-d), this tumor harbored 2 LP mutations and 1 VUS in the POLE gene." (PMID 37891325, 2023). "Thus, the function of POLE and POLD1 is essential to suppress gene mutations and consequently tumor genesis." (PMID 37108738, 2023). "For instance, because the POLE ultamutated group shows an excellent prognosis, though the tumor is in high grade, stage I-II POLE-mutated patients do not need adjuvant therapy." (PMID 37835582, 2023). "Similarly, somatic proofreading POLE and POLD1 mutations occur in colorectal and endometrial cancers, and to a lesser extent, in other tumor types." (PMID 36856825, 2023). "There are several common threads from these tumor studies that make POLE mutant tumors unique." (PMID 37388540, 2023). "Recent research has shown that mutations in single genes, such as POLE, NLRP3, COL3A1, and PTPRT could predict tumor TMB and immunotherapeutic response." (PMID 35884556, 2022). "In the TCGA cohort, the tumor mutation burden (TMB) of both POLE EDM tumors (p < 0.001) and POLE non-EDM tumors (p < 0.001) was significantly higher than that of POLE wild-type (WT) tumors." (PMID 36479248, 2022). "In addition, we studied the effect of POLE expression on the tumor immune environment, expressed through the anti-tumors' activity of immune cells." (PMID 35812186, 2022). "Another case that harbored missense mutations of the exonuclease domain of POLE (P286R and T323A), PIK3CA, ARID1A, and PTEN and a high tumor mutation burden (169 mutations per DNA megabase) achieved a durable response with pembrolizumab but was microsatellite stable." (PMID 36290878, 2022). "Furthermore, although the tumours we originally described in POLE and POLD1 carriers were microsatellite-stable, the frequency of MSI (12.5%) that we now describe in CRCs is similar to that in sporadic CRCs, despite the earlier onset of the former." (PMID 33948826, 2022). "In addition to the absence of other known actionable driver mutations, NTRK+ CRC tumors harbor very high tumor mutation burden (median 53 mut/MB), with most of them being microsatellite instability‐high (MSI‐H), and an enrichment of POLE/POLD1 mutations." (PMID 35506567, 2022). "In POD1UM-204, patients with advanced EC with disease progression on or after >1 platinum-based regimen are enrolled in four treatment groups based on prior immunotherapy exposure and tumor characteristics, such as MSH-I, dMMR, ultra-mutated POLE, and FGFR mutation." (PMID 36119020, 2022). "We identified 10 tumors out of 198 (5%) carrying POLE mutation in the exonuclease domain in the selected cohort whereas only one tumor out of 222 (0.5%) was mutated in the nonselected cohort (Chi‐square test, P = 0.0032)." (PMID 35624529, 2022). "POLE mutations are related to other favorable predicative factors such as high expression of PD-L1, high TMB, and infiltration of CD8+ cells in the tumor microenvironment." (PMID 35308232, 2022). "Those with POLE mutant tumours have such a good prognosis that adjuvant treatment is unlikely to improve survival outcomes and de-escalation of therapy may be appropriate." (PMID 35530346, 2022). "The current analysis showed that the POLE mutation may be through the MMR, TGF-β, and RTK/RAS/RAF signaling pathways affecting tumor development, while the POLD1 mutation may affect tumor development through the MMR signaling pathway." (PMID 35780178, 2022). "To test whether SBSA and SBSB were involved in the related defection, we compared the tumor gene mutations of LAS subtype patients to that of the other patients in MMR genes and POLE." (PMID 35814400, 2022). "We found that expression of POLE was lower in normal tissues than in tumor tissues." (PMID 35812186, 2022).
tumor (continued). "Furthermore, there were two genes (FBXW7, RET) mutated exclusively in tumours and eight (BLM, GJB2, NOTCH2, NOTCH3, NTRK1, POLE, SOS1, TSC2) solely in metastases." (PMID 34572946, 2021). "None of the four tumours harbouring pathogenic POLE mutations displayed MSI features in the four mononucleotide repeat markers." (PMID 34034807, 2021). "The coexistence of MSI+ and mutated POLE may be associated with higher densities of CD8+ TILs, PD-1-expressing CD8+ TILs, and tumor-infiltrating immune cells with a Th1 phenotype in the TME, strongly predicting response to checkpoint inhibitors." (PMID 34026645, 2021). "For example, POLE/POLD1 gene mutations are associated with microsatellite instability (MSI), mismatch repair (MMR), and TMB, and CMTM6 is related to PD-L1 expression and regulation of anti-tumor immunity." (PMID 34790698, 2021). "The hypermutated condition may be related to driver mutations in the DNA polymerase ε (POLE) and δ1 (POLD1) genes among different tumor types, including colorectal, endometrial, and other cancers such as melanoma and lung cancer." (PMID 34026645, 2021). "The analysis of mutations in tumor tissue and tumor organoids revealed that the initial tissue from liver metastasis of Patient 1 contained only one SNV in the POLE gene (p.F990S)." (PMID 34955846, 2021). "Therefore, regardless of how technically robust biomarkers such as MSI/MSS status, TMB, PDL1, POLE/POLD1 mutation, and MSI-like gene signature, these biomarkers will only characterize the quantity of tumor-infiltrating CD8+ T cells." (PMID 34594218, 2021). "The human POLE-P286R mutation is found in the heterozygous condition, so we would not predict tumour cells carrying this mutation would necessarily show an S phase delay." (PMID 34228709, 2021). "POLE–mutated tumours display very specific mutation signatures (SBS 10 and 28) in humans and mice, and these signatures have been recapitulated in human cells engineered to express mutant POLE." (PMID 33764464, 2021). "POLE proofreading domain-mutant tumours may be particularly sensitive to specific therapeutic approaches due to their exceptional mutation burden." (PMID 34228709, 2021). "We then extended our analysis to the characterization of another essential tumor suppressor gene: POLE, which is considered important for determining access to immunotherapy and four variants were used as control: two classified as benign and two as pathogenic." (PMID 34749799, 2021). "All six of the grade 3 EACs without POLE mutation and high tumor mutational burden demonstrated this genetic pattern." (PMID 33256706, 2020). "POLE and MSI mutated EC tumours show better survival outcomes." (PMID 32523655, 2020). "The mutation profile of the tumor with the highest TML value (case 16) had a high proportion of C > T, C > A, T > G, and T > C changes, but low proportion C > G and T > A transversions, a mutational profile closely resembling that of other POLE-mutated tumors." (PMID 32642724, 2020). "The variation in the genomic correlates of POLE mutations by their location is mirrored by variation in the prevalence of MSI in cancers carrying these mutations, and in differences in the genomic architecture of tumours harbouring both defects." (PMID 31829442, 2020). "As previously reported 1, 7, 12, 26, the five hotspot POLE mutations were reliably associated with elevated TMB (median = 268 mut/Mb), which exceeded 100 mut/Mb (typically used to define ultramutation) in most tumours (33/41)." (PMID 31829442, 2020).